PC (pyruvate carboxylase)
Description:
Pyruvate carboxylase catalyzes a 2-step reaction, involving the ATP-dependent carboxylation of the covalently attached biotin in the first step and the transfer of the carboxyl group to pyruvate in the second. Catalyzes in a tissue specific manner, the initial reactions of glucose (liver, kidney) and lipid (adipose tissue, liver, brain) synthesis from pyruvate.
Synonyms: PCB
Tractability: Small molecule: a structure with a bound ligand is known; it has a high-quality binding pocket. PROTAC: ubiquitination databases record sites on it; its protein half-life has been measured.
Target class: Enzyme; Ligase
Gene: Protein-coding gene on chromosome 11 (66,848,208 to 66,958,524, reverse strand). Ensembl gene ENSG00000173599.
Subcellular location: Mitochondrion matrix
Subcellular location (Human Protein Atlas): Mitochondria
Pathways (Reactome):
Metabolism: Biotin transport and metabolism; Gluconeogenesis; Pyruvate metabolism
Disease: Defective HLCS causes multiple carboxylase deficiency
Gene Ontology:
Molecular function: identical protein binding; protein binding; pyruvate carboxylase activity; ATP binding; biotin binding; catalytic activity; metal ion binding
Biological process: host-mediated activation of viral process; NAD+ metabolic process; NADP+ metabolic process; negative regulation of gene expression; viral release from host cell; viral RNA genome packaging; gluconeogenesis
Cellular component: cytoplasm; mitochondrial matrix; mitochondrion; cytosol
Genetic constraint (gnomAD): Loss-of-function variants: 46 observed, 109.14 expected, observed/expected ratio (o/e) 0.42, 90% interval 0.33 to 0.54. The upper end of that interval is the gene's LOEUF score, 0.54, which puts it in group 2 of 6, group 1 being the genes least tolerant of losing a copy. Missense variants: 1,241 observed, 1,662.6 expected, observed/expected ratio (o/e) 0.75, 90% interval 0.71 to 0.78. Synonymous variants: 662 observed, 691.19 expected, observed/expected ratio (o/e) 0.96, 90% interval 0.9 to 1.02.
Homologues: Orthologues: chimpanzee PC (99% identical), macaque PC (99% identical), dog PC (98% identical), guinea pig PC (97% identical), mouse Pcx (97% identical), rat Pc (96% identical), pig PC (95% identical), tropical clawed frog pc (84% identical), zebrafish pcxa (83% identical), zebrafish pcxb (83% identical), Drosophila melanogaster PCB (68% identical), Caenorhabditis elegans pyc-1 (64% identical). Paralogues in human: ACACB (27% identical), ACACA (27% identical), PCCA (24% identical), MCCC1 (21% identical).
Diseases named in the same sentence as PC in open-access papers:
PC is named in the same sentence as 115 diseases in open-access papers, as found by Europe PMC text mining. Sharing a sentence is not in itself a finding about the gene and the disease. The quoted sentences say what the papers report.
breast cancer (25 papers, 2015 to 2026). A primary or metastatic malignant neoplasm involving the breast. "Increased PC expression in breast cancer is associated with reduced patient survival time, suggesting a role of PC in metastatic progression of cancer cells." (PMID 33931119, 2021). "Pyruvate carboxylase (PC) is a mitochondrial enzyme and is associated with lung metastasis in breast cancer." (PMID 34970420, 2021). "39S ribosomal protein L34 was identified as a risk factor for breast cancer (IVW, p=0.021, OR = 1.069, 95% CI: 1.010–1.132), while pyruvate carboxylase showed a causal association with breast cancer as a risk factor (IVW, p=0.007, OR = 1.071, 95% CI: 1.019–1.127)." (PMID 39742384, 2024). "In breast cancer, pyruvate carboxylase (PC)-mediated anaplerotic entry into the tricarboxylic acid (TCA) cycle promotes an invasive phenotype by enhancing cell motility." (PMID 40814172, 2025). "In breast cancer lung metastasis models, a higher pyruvate carboxylase (PC)-dependent anaplerosis was initially discovered in lung metastases as compared to primary breast cancers." (PMID 38802766, 2024). "Recent studies have underscored the significance of mitochondrial genes, including 39S ribosomal proteins, pyruvate carboxylase, and cytochrome c oxidase subunits, in the development of breast cancer." (PMID 39742384, 2024). "Pyruvate carboxylase inhibition by 1α,25-dihydroxyvitamin D enhances oxidative stress in early breast cancer progression." (PMID 34123800, 2021). "For example, PC protein is overexpressed in human mammary cancer compared with normal mammary tissue and increases in abundance with tumor stage, as demonstrated by immunohistochemical analysis." (PMID 33931119, 2021). "Transglutaminase-2 can facilitate extracellular vesicle-mediated establishment of the metastatic niche, while pyruvate carboxylase enhances the pulmonary tropism of metastasis in breast cancer." (PMID 34123800, 2021). "Studies have determined that compared with primary breast cancer, the degree of pyruvate carboxylase (PC)-dependent anaplerosis in lung metastasis of breast cancer is higher, as a result of responding to the lung microenvironment." (PMID 33489906, 2020). "Meanwhile, other studies suggest that 1α,25(OH)2D3 enhances oxidative stress during the early progression of breast cancer by inhibiting the activity of pyruvate carboxylase." (PMID 32848720, 2020). "A specific metabolic inhibitor (named ZY‐444) of pyruvate carboxylase (PC), the key anaplerosis enzyme, is discovered to exhibit cancer selectivity as well as great therapeutic efficacy against breast cancer progression." (PMID 32382484, 2020). "Metastasis involves specific metabolic changes—for example, recent studies identified a requirement for proline in matrix-detached breast cancer cells, while breast cancer cells colonizing the lungs depend on pyruvate carboxylase for anaplerosis." (PMID 29892572, 2018). "Knockdown of PC inhibits proliferation, migration, and invasion behaviours in invasive breast cancer cells; conversely, the overexpression of PC promotes proliferation, migration, and invasion abilities in noninvasive breast cancer cells." (PMID 28137309, 2017). "However, preferential glucose contribution to the TCA cycle through the activity of pyruvate carboxylase (PC) – as compared to the activity of pyruvate dehydrogenase (PDH) – has been reported in mouse models of lung cancer and breast cancer-derived lung metastasis." (PMID 34256164, 2021). "Pyruvate carboxylase (PC) is an anaplerotic enzyme essential for oxidative stress protection, although its relationship with GPX4 in obesity-related breast cancer is not established." (PMID 40001204, 2025).
diabetes (9 papers, 2016 to 2025). "Obesity and diabetes are associated with increased pyruvate carboxylase expression in liver and adipose tissue." (PMID 33708149, 2021). "Also, deregulation of pyruvate carboxylase encoded by PC gene was previously linked to T2D in humans and its inhibition could be a potential therapeutic approach for diabetes." (PMID 39003492, 2024). "Animal studies have demonstrated that increased pyruvate carboxylase flux is an important pathway responsible for increased hepatic glucose production in diabetes development." (PMID 33708149, 2021). "This decrease in ceramide levels may alleviate ER stress, upregulate citrate synthase (CS) expression, downregulate pyruvate carboxylase (PC)expression, and further inhibit gluconeogenesis, ultimately preventing the onset of diabetes." (PMID 39726876, 2024). "Similarly, patients with diabetes mellitus type 1 and patients on ketogenic diet, conditions known for increased gluconeogenic flux and activated pyruvate carboxylase, also showed elevated BTD enzyme activity in serum." (PMID 33473341, 2021). "Manganese activates enzymes such as pyruvate carboxylase, increases insulin secretion, improves glucose tolerance under dietary stress conditions, reduces oxidative stress (ROS) and NADPH oxidase activity, and decreases the risk of endocrine dysfunction in diabetes." (PMID 40224537, 2025). "Moreover, the finding of decreased expression of the pyruvate carboxylase enzyme may be because the model of diabetes we used begins to lower insulin levels after 16 weeks of age." (PMID 29857581, 2018).
glioma (8 papers, 2014 to 2023). A benign or malignant brain and spinal cord tumor that arises from glial cells (astrocytes, oligodendrocytes, ependymal cells). "In addition, glioma cells with IDH1 mutation demonstrate the activation of pyruvate carboxylase which leads to the increase in the formation of oxaloacetate products." (PMID 35625744, 2022). "Analysis of All glioma tumors highlighted two genes involved in pyruvate metabolism that were associated with IDH1; these were glyoxalase I (GLO1) and pyruvate carboxylase (PC)." (PMID 35877430, 2022). "We used Repo and DAPI to label the nuclei region and observed a significant decrease of caspase-3 levels in glial neoplasms that overexpress Nmnat-PC (nuclear), compared with those overexpressing lacZ, Nmnat-PCWR (nuclear), or Nmnat-PD (cytoplasmic)." (PMID 34919052, 2021). "In addition, IDH1 mutant glioma cells show greater flux through pyruvate carboxylase leading to greater production of oxaloacetate." (PMID 37274274, 2023). "Lactate production under aerobic conditions, the so-called Warburg effect, is usually encountered in tumor cells, although IDH1mut gliomas have been traditionally defined as non-glycolytic, and thought to mainly divert pyruvate towards oxaloacetate through pyruvate carboxylase." (PMID 32575619, 2020).
hepatocellular carcinoma (8 papers, 2013 to 2025). A malignant tumor that arises from hepatocytes. "In human hepatoma HepG2 cells, erianin can selectively inhibit the activity of the pyruvate carboxylase-mediated Wnt/β-catenin pathway." (PMID 40733232, 2025). "Previous study has confirmed that Erianin can regulate the pyruvate carboxylase-mediated Wnt/β-Catenin pathway in human hepatoma." (PMID 39605083, 2024). "One of the three known promoter regions of bovine pyruvate carboxylase (PC), a key enzyme in gluconeogenesis, was activated by Wy-14643 when transfected as a construct with firefly luciferase into rat hepatoma cells, indicating a potential control of expression of this enzyme by PPARα in ruminants." (PMID 23737762, 2013). "In our previous study, we have identified that EnhII/BCP/PC mutations and genotype C of HBV DNA were associated with hepatocellular carcinoma (HCC) risk." (PMID 31033235, 2019). "Similarly, rat hepatoma (H4IIE) cells transfected with bovine PC promoter-luciferase constructs exposed to serum from feed restricted cows or serum from control cows with FA added had increased PC promoter 1 activity; however, the FA concentration in serum in that experiment was 1.3 mM." (PMID 33166331, 2020).
Obesity (7 papers, 2010 to 2025). Accumulation of substantial excess body fat. "In human white adipose tissue, ADIPINT expression is increased in obesity and linked to fat cell size, adipose insulin resistance, and pyruvate carboxylase activity." (PMID 35618718, 2022). "It has been suggested that pyruvate carboxylase is a potential therapeutic target for several diseases associated with obesity." (PMID 33708149, 2021). "Evidence supporting increased pyruvate carboxylase-mediated anaplerosis as a common mechanism underlying glutamatergic hyperactivity in bipolar disorder and the positive association between bipolar disorder and obesity is also discussed." (PMID 33708149, 2021). "Multiple independent lines of evidence suggest that increased pyruvate carboxylase-mediated anaplerosis is a common mechanism underlying glutamatergic hyperactivity and the significant positive association between bipolar disorder and obesity." (PMID 33708149, 2021). "As the increased prevalence of obesity in bipolar disorder is associated with illness severity and poor treatment outcomes development of preventive and treatment strategies targeting pyruvate carboxylase-mediated anaplerosis may be warranted." (PMID 33708149, 2021). "Over expression of pyruvate carboxylase is associated with obesity and type 2 diabetes." (PMID 33708149, 2021). "Multiple independent lines of evidence supporting increased pyruvate carboxylase-mediated anaplerosis as a common mechanism underlying glutamatergic hyperactivity in bipolar disorder and the positive association between bipolar disorder and obesity are also described." (PMID 33708149, 2021). "Therefore, both mechanistic and clinical studies of carbonic anhydrase inhibition support the proposed connections among bipolar disorder, obesity and pyruvate carboxylase-mediated anaplerosis." (PMID 33708149, 2021). "In another integrative methylome–transcriptome analysis, seven key genes were identified—CCRL2, GPT, LGALS12, PC, SLC27A2, SLC4A4, and TTC36—that were hypermethylated in obesity and concurrently showed reduced expression." (PMID 41303351, 2025). "In summary, we successfully identified seven key genes, namely, CCRL2, GPT, LGALS12, PC, SLC27A2, SLC4A4, and TTC36, which are involved in obesity occurrence and development likely through the immune microenvironment." (PMID 36313453, 2022). "In this study, by analyzing three GEO datasets and verifying in 24 patients, we identified that CCRL2, GPT, LGALS12, PC, SLC27A2, SLC4A4, and TTC36 might be the key genes that play an important role in obesity pathogenesis." (PMID 36313453, 2022).
Hepatic fibrosis (6 papers, 2013 to 2025). The presence of excessive fibrous connective tissue in the liver. "BCP and PC mutations and the stage of liver fibrosis and the presence of cirrhosis or HCC - Liver biopsies were carried out on 125 patients." (PMID 28902288, 2017). "Our results indicate that E-T/LNPs improved the histopathology, reduced the production of collagen fibers, decreased the levels of AST, ALT, PC III, Col IV, LN, HA and had a protective effect against CCl4-induced liver fibrosis." (PMID 39519763, 2024). "Therefore, the combination of noninvasive biochemical parameters (hyaluronic acid, laminin, PC III, type IV collagen) and liver function indexes (alanine aminotransferase, aspartate aminotransferase, total bilirubin) is the main evaluation index for the diagnosis and prognosis of hepatic fibrosis." (PMID 32629728, 2020).
lung carcinoma (6 papers, 2015 to 2024). "In this way, oxidative lung cancer cells can convert lactate into PEP via the upregulation of PC and PCK2." (PMID 38731909, 2024). "The gluconeogenesis is even further supported in lung cancer by the upregulation of pyruvate carboxylase (PC) since this enzyme is responsible for the transformation of pyruvate to oxaloacetate." (PMID 38731909, 2024). "Overexpression of the long non-coding RNA (lncRNA, CTD-2245E15) in lung cancer can also regulate ACC1 and pyruvate carboxylase to promote lung cancer development." (PMID 36106108, 2022). "Given the recent demonstration of the importance of pyruvate carboxylase (PC) in lung cancer cells, we also examined PC flux in the model." (PMID 26137220, 2015).
Insulin resistance (5 papers, 2018 to 2022). Increased resistance towards insulin, that is, diminished effectiveness of insulin in reducing blood glucose levels. "The association between insulin resistance and PC‐1 rs1044498 (K121Q) polymorphism was analyzed in our case–control investigation." (PMID 31250990, 2019). "To understand the role of pyruvate carboxylase and hepatic gluconeogenesis in insulin resistance, we placed male and female control and PcxL−/− mice on a high-fat diet (HFD) for 12 weeks." (PMID 36441025, 2022). "The activation of pyruvate carboxylase by acetyl-CoA derived from fatty acids has been proposed to play a major regulatory role in potentiating inappropriate gluconeogenesis in insulin resistance." (PMID 36441025, 2022). "As well as other proteins, such as 60 kDa heat shock protein, peroxiredoxin-1, pyruvate carboxylase and regucalcin; they have been found increased in different models of insulin resistance." (PMID 29857581, 2018). "But diets containing saturated fat, not only promote hepatic triglyceride accumulation, but also favor gluconeogenesis, resulting from allosteric activation of pyruvate carboxylase flux and increased glycerol flux, and induce insulin resistance by lipid-mediated inhibition of insulin signaling." (PMID 33839905, 2021).
gallbladder cancer (4 papers, 2017 to 2021). "Cell and patient-derived tumor tissue models of gallbladder cancer demonstrated the importance of the long non-coding RNA (lncRNA) gallbladder cancer-associated suppressor of pyruvate carboxylase (GCASPC) in regulation of PC expression." (PMID 33931119, 2021). "miR-17-3p, which targets GCASPC (gallbladder cancer-associated suppressor of pyruvate carboxylase), can suppress pyruvate carboxylase-dependent cell proliferation in gallbladder cancer by binding and destabilizing the pyruvate carboxylase (PC) protein." (PMID 30134946, 2018). "In gallbladder cancer, the lncRNA GCASPC regulates glycolysis by directly binding pyruvate carboxylase." (PMID 29371936, 2017). "In addition, the expression of the lncRNA GCASPC was significantly lower in the gallbladder cancer (GBC) tissues, and GCASPC overexpression was found to suppress cell proliferation by binding to pyruvate carboxylase." (PMID 28209205, 2017).
Hyperglycemia (4 papers, 2016 to 2023). An increased concentration of glucose in the blood. "In diabetic mice, kaempferol was observed to contribute to the improvement of hyperglycemia and reduce hepatic glucose production by decreasing the activity of pyruvate carboxylase." (PMID 37504903, 2023). "For instance, elevated protein expression or activity of pyruvate carboxylase (PC), a mitochondrial matrix-localized enzyme that catalyzes the carboxylation of pyruvate to oxaloacetate (OAA), is associated with hyperglycemia." (PMID 36812201, 2023). "This condition of hyperglycemia can also be a consequence of the disruption of key gluconeogenesis enzymes, such as pyruvate carboxylase, phosphoenolpyruvate carboxykinase, and glucose-6-phosphatase, as a result of the decreased EGFR activity." (PMID 38067203, 2023).
pancreatic cancer (4 papers, 2012 to 2022). "Pancreatic cancer cells exhibited increased pyruvate carboxylation relative to fibroblasts, and this flux depended on both pyruvate carboxylase and malic enzyme 1 activity." (PMID 32648540, 2020). "(B) Representative image from a human pancreatic tumor tissue microarray that was stained with an antibody against pyruvate carboxylase." (PMID 32648540, 2020). "The comparison revealed that ALDOB, SLC2A2, PC and PCK1 mRNA levels were significantly higher in the liver metastatic lesions in comparison to the primary pancreatic tumors." (PMID 22412968, 2012). "In pancreatic cancer, SLC38A2 represents the major AAT for alanine, which is then deaminated to pyruvate (which can maintain the tricarboxylic acid cycle) in the presence of pyruvate carboxylase." (PMID 33028955, 2021).
type 2 diabetes (4 papers, 2013 to 2024). "Tissue-specific inhibition of pyruvate carboxylase reduced plasma glucose concentrations and could be a potential therapeutic approach for nonalcoholic fatty liver disease, hepatic insulin resistance, and type 2 diabetes." (PMID 35799202, 2022).
biotin deficiency (3 papers, 2022 to 2025). "It is known that biotin deficiency can cause malfunction of multiple carboxylases (MCC, ACC, PCC, PC), and thereby impede the process of reactions catalyzed by these enzymes, resulting in toxicity related to accumulated substrates, and eventually, various clinical manifestations." (PMID 37373384, 2023). "By measuring the activity of the biotin-dependent pyruvate carboxylase in fibroblasts of patient 1–2 we did not obtain evidence for biotin deficiency in this patient." (PMID 35013551, 2022).
Cirrhosis (3 papers, 2015 to 2021). A chronic disorder of the liver in which liver tissue becomes scarred and is partially replaced by regenerative nodules and fibrotic tissue resulting in loss of liver function. "Importantly, pyruvate carboxylase (pycA), responsible for the production of oxaloacetate from pyruvate was overexpressed in NAFLD-HCC compared to NAFLD-cirrhosis and non-NAFLD control (P = 0.004)." (PMID 33420074, 2021).